INS (insulin)
Diseases named in the same sentence as INS in open-access papers (continued):
Sharing a sentence is not in itself a finding about the gene and the disease.
Insulin resistance (continued). "This suggests that C18-ceramide may not be the main SL lipid actor for the development of insulin resistance, or possibly that the residual muscle C18-ceramide content (50%) was sufficient to inhibit insulin sensitivity (in opposite to 90% ablation observed in Turpin-Nolan's study)." (PMID 32849282, 2020). "While fucoidan was reported to restore insulin stimulated glucose-uptake in adipocytes in vitro, no fucoidan-effects on insulin or glucose control were observed in healthy overweight subjects and in one clinical trial fucoidan even increased insulin resistance." (PMID 32121066, 2020). "The lack of effect of in vivo CRHR blockade on insulin resistance during pregnancy suggests that the impaired glucose tolerance reflects a β-cell targeted effect, consistent with our in vitro observations of enhanced insulin secretion in response to CRHR2 activation." (PMID 32106091, 2020). "Since the promotion of hepatic insulin sensitivity caused by JNK-deficiency in adipocytes and myeloid cells is associated with defects in adipokine/cytokine expression, it is possible that obesity-induced activation of JNK in non-hepatic cells mediates HFD-induced hepatic insulin resistance." (PMID 32872540, 2020). "Indeed STZ-model does not induce obesity, insulin resistance and hyperinsulinemia, suggesting that underlying mechanisms for Abn-CBD-driven changes in food intake are different in insulin resistant model and in the insulin production deficient model." (PMID 32210914, 2020). "In addition, obesity facilitates the establishment of hyperinsulinemia and insulin resistance, thereby determining an unopposed activation of the insulin receptor (IR) and the insulin-like growth factor receptor (IGF-1R), which are part of the complex insulin/IGF system (IIGFs)." (PMID 33364239, 2020). "Insulin resistance may contribute to chemotherapy resistance in individuals with colon cancer; as such, two colon cancer cell lines were used to determine whether the expression of IRS‐1 would affect the half maximal inhibitory concentration (IC50) of oxaliplatin after chronic insulin treatment." (PMID 32248666, 2020). "However, another study suggested any therapeutic approach that reduced insulin secretion demand and enabled β‐cell rest, irrespective of whether it alleviated insulin resistance or improved glucose homeostasis, preserved functional β cells." (PMID 33312555, 2020). "Although these mechanistic pathways, by which negative affect promotes insulin resistance, were not tested in the current study, our findings suggest that the adverse effects of negative affect override any potential protective effects of a Mediterranean diet on insulin sensitivity." (PMID 32041106, 2020). "Interestingly, skeletal muscle-specific knockout of PKCδ improves age-related decline in whole-body insulin sensitivity and glucose tolerance, and also increases insulin sensitivity of skeletal muscle in older mice but does not protect from HFD-induced insulin resistance." (PMID 32466765, 2020). "Therefore, pathogenesis of insulin resistance in the absence of obesity in NOD individuals could be related to other pathways of insulin signaling." (PMID 32670384, 2020). "However, metformin did not regulate the secretion indexes of fasting insulin, homeostasis model assessment of insulin resistance, sex hormone-binding globulin, high-density lipoprotein cholesterol, total cholesterol, triglycerides, fasting blood glucose, and androstenedione." (PMID 33014044, 2020). "However, ‘insulin resistance’ may only refer to the glycemic context of T2D, whereas the non-glycemic aspects of T2D are fully responsive to insulin and driven by hyperinsulinemia." (PMID 32128655, 2020). "Finally, the absence of measured insulin levels and the subsequent estimation of insulin resistance that could explain, at least in part, the observations of the present study, may be considered as a possible limitation of our study." (PMID 32764712, 2020).
Insulin resistance (continued). "Additionally, we do not have data on use of insulin prior to admission or an estimate of relative degree of insulin resistance—these are important confounders which may impact physician practice and insulin dosing." (PMID 32612144, 2020). "We hypothesize that with the worsening insulin sensitivity in adipose tissue following GSI (i.e. with the previously observed increased in NEFA,) and these newly observed changes in IL-6 secretion, that GSI can lead to a significant degree of localized adipose insulin resistance." (PMID 32603641, 2020). "It has long been known that insulin is required for neuronal survival and development, and although it has been shown that offspring of obese mothers develop insulin resistance in utero, the consequences of insulin resistance for neuronal development were not previously known." (PMID 32919096, 2020). "However, insulin resistance in MetSyn and DM2 is characterized by elevated basal endogenous glucose production (EGP), impaired suppression of endogenous glucose production (EGPsupp, a surrogate marker for hepatic IS), and reduced peripheral insulin-stimulated glucose uptake." (PMID 32752028, 2020). "Interestingly, the improvement in depressive symptoms was independent of the insulin-sensitizing effects of pioglitazone; in both studies, changes from baseline in homeostatic model assessment of insulin resistance (HOMA-IR) values were not correlated with the changes in depressive symptoms." (PMID 32971941, 2020). "Additionally, the rate of lipolysis is higher in VAT than subcutaneous adipose tissue, increasing the circulation of non-esterified fatty acids, which may affect hepatic insulin removal and lead to insulin resistance and hyperinsulinemia." (PMID 33261185, 2020). "Finally, we did not directly measure insulin levels or insulin resistance, therefore, the linkage between hyperinsulinemia and cancer incidence could only be inferred from the drug-cancer associations." (PMID 31518336, 2019). "In addition, hyperglycaemia in most cases is characterised by a significantly blunted acute first phase of insulin secretion in response to an oral or intravenous glucose load and pancreatic beta cell secretory dysfunction, rather than peripheral insulin resistance predominates." (PMID 30783538, 2019). "Hence, insulin resistance in NRK1 LKO mice might not be necessarily consequent to a direct action of a NAD+-dependent protein on insulin signaling, but secondary to the exacerbation of high-fat diet-induced steatosis." (PMID 31541116, 2019). "Thus, this could have been the result of insulin resistance or impaired insulin secretion by the Ppp1r15aΔC/ΔC mice, although basal and 30 minute insulin levels after glucose administration were not measurably different." (PMID 30814564, 2019). "One limitation of the current study is that hormone response during the oral glucose tolerance test was not explored, and therefore, measurements of insulin sensitivity, like the homeostatic model of assessment of insulin resistance (HOMA-IR) could not be quantified." (PMID 31159256, 2019). "Thus, we could not calculate the area under the curve for insulin and glucose, nor could we calculate the homeostasis model assessment-estimated insulin resistance (HOMA-IR) in PCOS patients with metformin treatment." (PMID 30959948, 2019). "Since insulin inhibits autophagy, the down-regulation of autophagic proteins observed in skeletal muscle may be due to hyperinsulinemia in diabetic patients who have not yet developed insulin resistance." (PMID 31487953, 2019). "Although, similar to the WT controls, Tm-CMV-KO mice became glucose intolerant, their fasting insulin levels and post-insulin glucose levels were markedly lower than those of WT, suggesting that Tmem127 loss protected mice from HFD-induced insulin resistance, independent of the weight gain." (PMID 31624249, 2019).
Insulin resistance (continued). "We conclude that SFA recovers glucose homeostasis and improves insulin sensitivity by blocking ceramide biosynthesis through modulating SPTLC3, indicating that SFA may be a potential candidate for prevention and amelioration of hepatic insulin resistance via a ceramide-dependent mechanism." (PMID 31137828, 2019). "Furthermore, inadequacy of compensatory insulin secretion, which could not increase in proportion with the severity of insulin resistance, is prominent in Asian diabetic population." (PMID 31632345, 2019). "The assessment of cardiac insulin resistance may require at least two independent points of myocardial FDG uptake, i.e., fasting (6–12 h fasting to minimize the heterogeneity of FDG accumulation) and maximal glucose uptake (by glucose and, if feasible, insulin loading)." (PMID 31330848, 2019). "However, the mechanism of insulin resistance leading to cognitive dysfunction is not clear, but may be correlated with insulin resistance increasing glycogen synthase kinase-3 activity, and competitive insulin degrading enzymes." (PMID 33817159, 2019). "Thus, considering the association between defective fatty acids β-oxidation, lipotoxicity and insulin resistance, targeting SIRT3 and mitochondrial protein acetylation may represent a promising approach in enhancing insulin sensitivity and improving metabolic health." (PMID 31130874, 2019). "The finding that obese female mice were insulin resistant despite lack of marked hyperinsulinemia contrasts what is typically seen in the human population where hyperinsulinemia is an early indicator of prediabetes and T2DM and is closely linked with concurrent insulin resistance." (PMID 31315689, 2019). "However, it is not known whether differential O-GlcNAcylation of insulin signaling intermediates and mitochondrial proteins play a role in sex differences in insulin resistance and metabolic dysregulation." (PMID 31118075, 2019). "Therefore, our data are in agreement with the fact that hyperinsulinemia can cause insulin resistance, given that the HF+STZ model studied here lacks increased insulin secretion and does not exhibit insulin resistance, despite the fact that other dysmetabolic features are present." (PMID 31141900, 2019). "Interestingly, a downregulation of the insulin-dependent phosphorylation cascade may not be a critical driver of the observed insulin resistance, since we did not observe significant downregulation of P-IRS1 or P-mTOR." (PMID 30533032, 2018). "Insulin signaling pathway results in phosphorylation of the insulin receptor-interacting protein (IRS-1), particularly, a decrease in IRS-1 phosphorylation may induce insulin resistance, while an increased phosphorylation on serine 312 of IRS-1 has opposite effects." (PMID 29949869, 2018). "Furthermore, the hepatic lipid storage and export observed in hepatic insulin resistance may not involve stimulation of DNL by insulin, but may instead reflect packaging of fatty acids coming to the liver from insulin-resistant adipose tissue." (PMID 31061673, 2018). "However, due to the results of several studies showing no mitochondrial function impairment in insulin resistant humans, the most accredited recent theory on mitochondrial involvement in the etiopathogenesis of insulin resistance focuses on reactive oxygen species (ROS) production." (PMID 29538286, 2018). "The metabolic health (as measured by body weight, adiposity, plasma fasting glucose, insulin, triglycerides, phospholipids, total cholesterol levels, and glucose and insulin tolerance tests) deteriorated with diet for both genotypes, while mice lacking Csf2 were protected from insulin resistance." (PMID 30065264, 2018). "However, neither total T nor A4 was related to BMI, insulin, or insulin resistance." (PMID 30275830, 2018). "However, their influence on insulin levels and insulin resistance has not been clarified yet." (PMID 30425742, 2018).
Insulin resistance (continued). "Additionally, HUVECs exhibited ER stress and insulin resistance when incubated with tunicamycin; however, co-incubation with ucOC (5 ng/mL) for 4 h reduced the ER stress and increased the phosphorylation of insulin receptor substrate 1 (IRS-1), a molecule involved in insulin signal transduction." (PMID 30287742, 2018). "In addition treatment with formononetin enhanced insulin sensitivity index and reduced HOMA-IR significantly at all dose level indicates improved glucose metabolism and proper utilization of insulin by tissues and reduction in insulin resistance at tissue level." (PMID 30072892, 2018). "This additional insulin resistance seems to be not complete, since i) it is transiently overcome by exogenous administration of insulin and ii) it is not reflected in a significant reduction of Akt phosphorylation in the muscle indicative of defective insulin signaling." (PMID 29959379, 2018). "In addition, obesity studies using catecholamine levels as a measure of sympathetic nervous activity have generally shown that the fall in BP with weight loss correlated with decreased plasma noradrenaline, although generally insulin levels and insulin resistance were not measured." (PMID 29518898, 2018). "Our study reveals that weight gain is not mandatory for the development of hypothalamic insulin resistance and the blockade of proinflammatory pathways could be useful for restoring the insulin signaling during prolonged low-grade inflammation as seen in obesity." (PMID 28677618, 2017). "T2D begins with insulin resistance in the absence of any clinical symptoms; however, over time insulin sensitivity gradually diminishes, and eventually reaches a point where insulin signaling does not work even though the body is producing increased levels of insulin." (PMID 28070499, 2017). "In both studies, metformin did not result in any change in insulin resistance whereas rimonobant, pioglitazone and orlistat all resulted in an improvement in insulin sensitivity; however the insulin sensitising action of metformin may be lost or reduced as BMI increases." (PMID 28705172, 2017). "In our present study, visceral fat mass, fasting serum insulin level and HOMA-IR of HFD-induced obese rats were also significantly reduced after LLAE intervention for 6 weeks, suggesting that LLAE could ameliorate insulin resistance by reducing VAT mass of HFD-induced obese rats." (PMID 28690544, 2017). "Although statistical significance was not reached with ITT analysis for markers of insulin resistance, exploration of subgroup analysis among patients with elevated cardiometabolic markers suggested a significant favorable effect of purified anthocyanins on fasting glucose and insulin regulation." (PMID 28994705, 2017). "To investigate whether mitochondrial function is regulated by insulin signaling, we analyzed muscle and liver of insulin receptor (IR)+/−-insulin receptor substrate-1 (IRS-1)+/− double heterozygous (IR-IRS1dh) mice, a well described model for insulin resistance." (PMID 28556799, 2017). "In addition, the increase of visceral fat accumulation in some non-obese T2D patients may be a consequence of either high insulin levels during insulin resistance or increased inflammatory responses." (PMID 28061846, 2017). "However, a 10-year prospective study from Korea of 1,298,385 patients showed that the risk of tumor was influenced by fasting blood glucose concentrations rather than insulin resistance, which challenges the theory that insulin directly effects on promotion of cancers." (PMID 28515345, 2017). "Finally, HOMA2-%S and HOMA2-IR could not accurately reflect insulin sensitivity and insulin resistance." (PMID 26649318, 2016). "However, in insulin resistance, the target organs and/or tissues do not fully respond to insulin." (PMID 27247938, 2016).
Insulin resistance (continued). "Previous research has supported that insulin sensitizers (e.g., metformin) provide fertility benefits to PCOS patients (i.e., improve pregnancy rate), especially those with hyperinsulinemia or insulin resistance, which could be responsible for the abnormal ovarian response." (PMID 27553217, 2016). "The lower insulin sensitivity in obese PCOS women compared to nonobese PCOS women shows that though obesity may not be the only cause of insulin resistance in PCOS subjects, it worsens the insulin resistance in PCOS and therefore should be a treatment goal." (PMID 27672393, 2016). "In diet-induced obese mice, which display hyperinsulinemia, acute exercise also increases insulin clearance and IDE expression, normalizing the insulinemia, and this could be an important beneficial effect of acute exercise, in diseases related to insulin resistance." (PMID 27467214, 2016). "Also, the skeletal muscles from foetuses from obese sheep have blunted insulin and AMPK signalling as well as an increased inflammatory cytokine tumour necrosis factor‐alpha (TNF‐α), in their plasma, suggesting the development of insulin resistance in these offspring." (PMID 27102569, 2016). "Furthermore, the elevated levels of insulin can also stimulate hepatic lipogenesis, contributing to the synthesis of VLDL particles, which leads to an elevation in circulating TGs and can increase the accumulation of skeletal muscle TGs, exacerbating the insulin resistance." (PMID 27582062, 2016). "Surprisingly, the insulin resistance, hypertriglyceridemia and liver steatosis in these males could be reversed by PPARγ agonist treatment, demonstrating that PPARγ2 is not essential for TZDs action on insulin sensitivity." (PMID 27483259, 2016). "The LD group instead, might have developed insulin resistance, as previously reported, resulting therefore in the lack of hypoglycemic effect of exogenous insulin, and in turn, no further increase in hypothalamic pAMPK expression." (PMID 27375435, 2016). "Thus, platelet insulin resistance is one of the main contributors to OxS-derived platelet hyperactivation in MetS, even though there is no pathophysiological model to explain how platelets become insulin resistant." (PMID 28053690, 2016). "In the present study, subjects with insulin resistance showed higher body fat percentage than their controls, therefore, the inhibitory effect of leptin on adipose FNDC5 expression may also explain the decreased circulating irisin in subjects with insulin resistant." (PMID 27473122, 2016). "Insulin resistance (IR), a reduced physiological response of the peripheral tissues to normal levels of insulin, is a growing concern in childhood obesity, although not all obese people are insulin resistant and IR may also occur in nonobese children and adults." (PMID 27590045, 2016). "T2D is characterized by insulin deficiency or insulin secretory defects, either with or without insulin resistance, and may be treated with oral medications, lifestyle, and dietary modifications; however, a large proportion of patients become insulin-dependent due to β-cell dysfunction." (PMID 27070593, 2016). "Moreover, other studies have reported that an insulin secretory defect, rather than insulin resistance, may play an important role in the development of type 2 diabetes in Koreans." (PMID 27275953, 2016). "However, in this study the serum insulin and insulin resistance has not been evaluated." (PMID 28058131, 2016). "Interestingly, insulin sensitivity in GRK2+/− mice is preserved after a HFD compared to WT littermates, indicating that a lower GRK2 dosage is able to protect animals against the development of diet-induced insulin resistance even in adult mice and after long-lasting HFD-induced obesity." (PMID 27832814, 2016). "Thus, insulin resistance could not be proved in the current study, especially due to the absence of intraperitoneal insulin tolerance test." (PMID 26216433, 2015).